IL6 (interleukin 6)
Diseases named in the same sentence as IL6 in open-access papers (continued):
Sharing a sentence is not in itself a finding about the gene and the disease.
Arterial thrombosis (13 papers, 2014 to 2025). The formation of a blood clot inside an artery. "Increased level of BAL IL-6 in aged SHRs immediately following UfCP exposure may induce the risk of both venous and arterial thrombosis by increasing expression of tissue factor, fibrinogen and platelet activation." (PMID 25442699, 2014). "Using a murine model of arterial thrombosis, we found blunted thrombus formation in mice receiving direct IL-6 blockade." (PMID 40534557, 2025). "The lowest p values (≤0.001) were observed for IL-6, integrin β1, integrin β2, and integrin β3, thus their significant impact on arterial thrombosis." (PMID 37998519, 2023). "The results showed that neutrophil and lymphocyte counts, Hb, CRP, IL-6, integrin β1, integrin β2, and integrin β3 levels were independent predictors of arterial thrombosis (p < 0.05)." (PMID 37998519, 2023). "Compared with those in the control group, the levels of IL-6 in patients with arterial thrombosis increased by six-fold (39.78 vs. 4.98 pg/ml)." (PMID 36211709, 2022). "Compared with that in the control group, the level of interleukin-6 in patients with arterial thrombosis increased by six-fold (39.78 vs. 4.98 pg/ml)." (PMID 36211709, 2022). "In this study, we aimed to detect the major inflammatory markers C-reactive protein (CRP), IL-6 (a cytokine closely related to arterial thrombosis), integrin β1, integrin β2, and integrin β3 in patients with acute arterial thrombosis (specifically AMI) and acute VTE." (PMID 37998519, 2023). "In that study authors have further shown that the induced pulmonary cytokine production (IL-6 from alveolar macrophages) following PM exposure might be responsible for increased intravascular thrombin formation, and accelerated arterial thrombosis." (PMID 25442699, 2014). "Streptococcus receptor polysaccharides may stimulate aortic endothelial cells, and cytokines (IL-6, IL-8, and monocyte chemoattractant protein-1) and intercellular adhesion molecule-1 showed increased expression, thus contributing to cardiovascular disease progression and arterial thrombosis." (PMID 40822584, 2025). "This was in line with the finding of profoundly increased levels of inflammatory biomarkers around arterial thrombosis, especially for PLR, NLR, and IL-6." (PMID 37525162, 2023). "For example, inflammatory cytokines, such as interleukin-6 (IL-6), are significantly increased in VZV infections that are related to arterial thrombosis." (PMID 31013629, 2019).
bone metastasis (13 papers, 2011 to 2025). Transfer of a neoplasm from its primary site to bones. "A proposed target for the treatment of CR PC patients is IL-6, an inflammatory cytokine that has been associated with CR progression, development of bone metastasis and metastasis-related morbidity." (PMID 27577074, 2017). "The elevated levels of both serum Shh and IL-6 were mainly observed in BC patients who had a significantly higher risk of early recurrence and bone metastasis, and associated with a worse survival for patients with progressive metastatic BC." (PMID 28496132, 2017). "The “IL-6 gene signature,” which identified patients at the highest risk for bone metastasis, might be a method to more efficiently select patients for such an approach." (PMID 22235336, 2012). "Furthermore, aberrant expression of the IL-6 gene and increased production of IL-6 are associated with advanced bone metastasis and increased morbidity, as well as resistance to chemotherapy." (PMID 21586128, 2011). "There is a strong correlation between elevated serum Shh and IL-6 and increased radiotracer uptake and bone metastasis in the patients." (PMID 28496132, 2017). "The role of IL-6 in human cancer is reinforced by the observation of elevated serum levels of IL-6 and soluble IL-6 receptor in patients with bone metastasis and a poor clinical outcome." (PMID 23374147, 2013). "The multitude of biological effects of IL-6 produced more interference factors in the diagnosis and monitoring of bone metastasis, so the serum level of IL-6 had no diagnostic value." (PMID 32546271, 2020). "The second gene set was associated with IL-6 and did not significantly change the overall survival rate (p = 0.165), but was significantly associated with a shorter time to bone metastasis (p = 0.049; 74% vs. 83% at 10 years)." (PMID 22235336, 2012). "Regulating IL6 may be the key to the treatment of bone metastasis by GTF." (PMID 35872837, 2022). "Two adipocyte-derived inflammatory cytokines, interleukin-6 (IL-6) and tumor necrosis factor-alpha (TNF-α), promote the development of bone metastasis." (PMID 38791037, 2024). "A panel of cytokines including interleukin 1 (IL1), interleukin 6 (IL6), parathyroid hormone like hormone (PTHrP) and colony-stimulating factor 1 (CSF-1) can induce the activation of osteoclasts in bone metastasis." (PMID 35685372, 2022). "Similarly, serum concentration of IL6 and IL8 in patients with bone metastasis of breast, lung and undefined carcinoma that we enrolled had significantly higher levels for IL6 and IL8 than healthy controls." (PMID 28903357, 2017).
cardioembolic stroke (13 papers, 2020 to 2025). "Positive association of IL-1 with cardioembolic stroke and suggestive inverse associations of IL-6 with any IS, cardioembolic stroke, and small vessel stroke, and of IL-16 with CAD." (PMID 34456968, 2021). "Results of a two-sample Mendelian randomization study showed a positive association of IL-1ra with cardioembolic stroke and inverse associations of IL-6 with cardioembolic stroke." (PMID 34277733, 2021). "Several studies reported that elevated levels of the inflammatory biomarkers, c-reactive protein (CRP), tumor necrosis factor-α (TNF-α), interleukin-6 (IL-6), interleukin-1β (IL-1β), are associated with cardioembolic stroke." (PMID 33050269, 2020). "Indeed, the serum level of miR-133 was shown to be positively correlated with IL-6 in patients with the therosclerotic thrombotic cerebral infarction and cardioembolic stroke." (PMID 37034572, 2023). "We found that patients with cardioembolic strokes at baseline had higher levels of CRP, IL-6, and neopterin at 3 months, indicating a difference in the inflammatory profile between these subgroups." (PMID 34879833, 2021).
diarrhoea (13 papers, 2015 to 2025). "Some of the DEGs in diarrhoea-susceptible sheep, enriched in GO terms and sub-network analysis, included IL-6, LOC101121216 (serum amyloid A), SIGLEC1, CHI3L1, S100A9, CD14, CD68, CD86, Ovar-DRB1, IL1RL1, LOC101103238 (CXCL5), CCL22 and IL1RN." (PMID 35576023, 2022). "IL-6 production can also be promoted by another gene that is up-regulated in diarrhoea-susceptible animals, serum amyloid A (SAA) another indicator of inflammation, a molecule with cytokine-like properties and immunomodulatory roles." (PMID 35576023, 2022). "In summary, a DSS challenge in the pig was associated with decreased body weight, diarrhoea and increases in the pro-inflammatory cytokine IL-6, and also in the abundance of Enterobacteriaceae in colonic digesta." (PMID 27110358, 2016). "This change can lead to microbiota changes, increased intestinal permeability, and decreased absorptive function accompanying the overproduction of inflammatory cytokines such as IL-6, TNF-α, and IL-1β with ageing, thereby causing diarrhoea." (PMID 34946386, 2021). "In summary, ad libitum feeding of pre-and post-weaned piglets with a Bacillus subtilis fermented liquid diet decreased intestinal bacterial diversity and increased intestinal fungal diversity, circulating IL-6 levels, intestinal unconjugated bile acid concentrations and diarrhoea incidence." (PMID 28291252, 2017). "However, when the IBS group was split into subgroups of patients with IBS-C and IBS with diarrhoea (IBS-D), patients with IBS-D had the highest TNF-α and IL-6." (PMID 32443433, 2020). "Although the incidence of diarrhoea was not affected, maternal LAM supplementation increased the ileal villi height and downregulated pro-inflammatory cytokines (ileal IL-6, colonic IL-8), suggesting that weaned pigs had enhanced gut integrity and gut health." (PMID 36230326, 2022).
fracture (13 papers, 2012 to 2025). "Following a bone fracture, an inflammatory response is triggered, characterized by elevated levels of pro-inflammatory cytokines (IL-6 and TNF-α) released by neutrophils and macrophages." (PMID 40430554, 2025). "Enhanced systemic IL-6 levels have been described after hip fracture, particularly in elderly patients, and has been considered as an independent predictor for adverse postoperative outcomes such as complications and mortality." (PMID 36131923, 2022). "In general, hip fracture induced remarkable cytokine (IL-6 and IL-10) release, miRNA (miR-146a and miR-150) abnormal expression, and ALI." (PMID 30510490, 2018). "Our results revealed that the concentration of IL-6, a key cytokine in the local immune response after bone fracture and in posttraumatic systemic inflammation, was neither locally nor systemically altered in Col1a1-C5aR1 mice." (PMID 28614388, 2017). "In conclusion, in the treatment of pertrochanteric fracture, secretion of inflammatory markers, especially IL-6, is less marked when minimally invasive techniques are used compared with traditional surgery." (PMID 22688402, 2012). "The result of this study indicates that elevated RPP at admission is a risk factor of POD in elderly patients undergoing hip fracture surgery and the effect of RPP at admission on POD may be partially mediated by preoperative plasma IL-6." (PMID 41229511, 2025). "The role of IL-6 in this setting may be quite central, since recent studies have reported improved fracture healing in an animal model of bone fracture following administration of neutralizing antibodies directed against the IL-6 receptor." (PMID 31163056, 2019). "Circulating IL-6 and CatB concentrations in patients with spine fracture were also significantly higher compared with the Control Group, showing that increase of IL-6 and CatB in serum is not specific to IVD." (PMID 31482941, 2019).
glomerular diseases (13 papers, 2013 to 2025). "Other factors contributing to renal damage include severe volume depletion, cytokine storm, collapsing glomerulopathy, and secondary hypoxia of renal vascular endothelium due to elevated IL-6." (PMID 40698223, 2025). "Moreover, IL-6 has been demonstrated to play a crucial role in glomerular inflammation in various glomerular diseases." (PMID 38915438, 2024). "Collectively, podocyte is a vigorous origin of IL-6, the local excessive expression of IL-6, and its receptor may actively involve in the process of diverse glomerular diseases in an autocrine and/or paracrine fashion." (PMID 28484449, 2017). "Notably, apart from above detrimental role in glomerular diseases, soluble IL-6 generated by podocytes also has anti-inflammation function which was demonstrated in co-culture system of podocytes and endothelial cells." (PMID 28484449, 2017). "Podocytes are a known source of IL-6 that could play a critical role in modulation of progressive glomerular disease." (PMID 24872191, 2014). "Moreover, there is a positive relationship between mesangial expansion (glomerulopathy) and expression of IL-6 mRNA in both mesangial cells and podocytes, implying an important role of IL-6 in influencing extracellular matrix dynamics at mesangial and podocyte levels." (PMID 28164134, 2017). "In this study, we focused on the role of CT‐1, a member of the IL‐6 cytokine family that had not been examined previously in the context of glomerular disease." (PMID 38955668, 2024). "Antibody-mediated depletion of TNF-α, IL-6, and IL-4Rα after common cold model induction in BALB/cJ mice resulted in a significant decline in albuminuria, suggesting potential therapeutic avenues for treating relapse of primary glomerular diseases after a common cold." (PMID 37040185, 2023).
gram-negative bacterial infections (13 papers, 2016 to 2025). Infections caused by bacteria that show up as pink (negative) when treated by the gram-staining method. "Pathogenic Gram-negative bacterial infections induced a strong IL-6 response at 24 h, indicating a robust pro-inflammatory reaction." (PMID 40873569, 2025). "This suggests that the tested compounds have anti-inflammatory effects that limit IL-6 secretion, particularly in response to Gram-negative bacterial infections." (PMID 40873569, 2025). "When compared with healthy people, IL-6 and IL-10 were significantly increased in Gram-negative bacterial infections, while only IL-6 was significantly increased Gram-positive bacterial infections." (PMID 36590299, 2022). "Bovine endometritis is an exemplar mucosal disease, characterized by sustained neutrophil infiltration and elevated IL-6 and IL-8, a neutrophil chemoattractant, following postpartum Gram-negative bacterial infection." (PMID 26813342, 2016). "This indicates that these treatments may have anti-inflammatory effects by reducing IL-6 secretion in response to Gram-negative bacterial infection." (PMID 40873569, 2025). "Studies have found that the level of IL-6 in the blood of patients with Gram-negative bacterial infection is significantly higher than those with Gram-positive bacterial infection, indicating that IL-6 has a certain suggestive effect on the pathogenic bacteria." (PMID 33902476, 2021). "Thus, LPS, the major component of endotoxin in gram-negative bacterial infection, can enter the blood stream and elicit systemic inflammatory response with increased production of pro-inflammatory mediators such as IL-6." (PMID 28253866, 2017). "The highest IL-6 concentration (217 pg/mL at 24h) was observed in the control condition, suggesting a strong inflammatory response upon Gram-negative bacterial infection, but not for Gram-positive." (PMID 40873569, 2025). "Therefore, CI, CSF PCT, and CSF IL-6 alone and their combination demonstrates certain advantages in the diagnosis of intracranial infections, especially in the condition of CSF RBC counts exceeding 3,000 × 106/L or Gram-negative bacterial infections." (PMID 40223136, 2025).
hearing loss (13 papers, 2014 to 2025). "The age‐related hearing loss mice displayed inflammatory infiltration in the cochlea associated with elevation of the IL‐6 and enhancement of the Cav1.3 calcium channel in inner hair cells." (PMID 39148148, 2024). "In contrast, 27.59% of the IL‐6 KO 9 M mice still displayed hearing loss (HL) (the IL‐6 KO 9 M HL group)." (PMID 39148148, 2024). "Anti-inflammatory cytokine therapy, including IL-6 blockade and antioxidant treatment, was suggested as a possible treatment for acute sensorineural hearing loss caused by noise." (PMID 38817543, 2024). "The relevance of IL-6 overexpression in noise-induced hearing loss was shown through the use of an anti-IL-6 receptor antibody." (PMID 25275304, 2014). "Moreover, levels of inflammatory mediators such as interleukin-1β, IL-1 receptor antagonist, IL-6, heat shock protein 70, and tumor necrosis factor-α have been shown to correlate closely with hearing loss severity and disease progression." (PMID 41011137, 2025). "Additionally, previous studies have demonstrated that increased ROS production and pro‐inflammatory cytokines, such as TNF‐α, IL‐1β, and IL‐6, play critical roles in cochlear tissue damage, in noise‐ or cisplatin‐induced hearing loss." (PMID 31353811, 2019). "By promoting the release of cytokines such as IL-1β, IL-6, and TNF-α, and regulate the processes of programmed cell death, the NOD pathway can lead to hearing loss." (PMID 40353062, 2025). "In noise-induced hearing loss, the damage to fibrocytes of the spiral ligament is likely to lead to changes in cytokines or chemokines such as TNF-a, IL-1b, IL-6, and Icam-1." (PMID 34150778, 2021). "Blood cytokine levels in humans with tinnitus may not be altered (except for IL-6 in one study), but a potential effect of tinnitus on the presence of cytokines may also be masked by the simultaneous presence of hearing loss." (PMID 35207270, 2022).
herpes zoster (13 papers, 2014 to 2026). A common dermal and neurologic disorder caused by reactivation of the varicella-zoster virus that has remained dormant within dorsal root ganglia, often for decades, after the patient's initial exposure to the virus in the form of varicella (chickenpox). "Acute herpes zoster is linked to increased levels of pro-inflammatory cytokines, such as IL-1, IL-6, and TNF-α, which are also central to the development of CPPD." (PMID 39553018, 2024). "Some cytokines such as IFN-gamma, IL-6, and IL-8 were slightly raised in the zoster group compared with a group of normal healthy subjects of similar age distribution, these differences only verged on significance." (PMID 36669977, 2023). "Increased IL-6 has also been postulated to be a predictive blood biomarker in herpes zoster, indicating propensity to develop post-herpetic neuralgia." (PMID 28361271, 2018). "Our result also supports an earlier report that found IL-6 transcripts in skin biopsies from human subjects with herpes zoster." (PMID 30568636, 2018). "IL-6 levels in patients with herpes zoster are significantly increased, related to pain severity." (PMID 38001018, 2024). "The possibility of herpes zoster developing into PHN can be judged early by the level of IL6." (PMID 36669977, 2023).
interstitial cystitis (13 papers, 2012 to 2025). A rare chronic debilitating urogenital disease characterized by urinary frequency, urgency, and pelvic pain. "IL-6 has been investigated as a urine biomarker for bladder pain syndrome showing promising results as a tool in identifying Hunner’s ulcerative cystitis or other subtypes of bladder pain syndrome." (PMID 36766573, 2023). "At all experimental concentrations, it ameliorated interstitial cystitis symptoms by reducing bladder weight, vascular permeability, and expression levels of IL-6, TNF-α, TGF 1-β, and iNOS, while increasing SOD, CAT, and GSH levels." (PMID 37375759, 2023). "Interstitial cystitis/painful bladder syndrome (IC/PBS) is characterized by increased bladder pain and urinary frequency and associated with increased IL-2, IL-6, IL-8, TNFα expression, and lowered levels of IL-4." (PMID 25962909, 2015). "Interstitial cystitis is a form of inflammatory hypersensitivity characterized with high levels IL-6 and histamine in patients' urine." (PMID 22969822, 2012). "The core genes (CXCL8, CXCL1, IL6) obtained in this study may be potential biomarkers of interstitial cystitis with guiding significance for clinical treatment." (PMID 33848079, 2021). "Interstitial Cystitis or Bladder Pain Syndrome (IC/BPS) is a heterogeneous condition characterized by elevated levels of inflammatory cytokines, IL-1β, IL-6, IL-8, IL-10, TNF-α, and is associated with debilitating symptoms of pelvic pain and frequent urination." (PMID 33923265, 2021). "The elevated expression of interleukin‐6 (IL‐6) in patients with interstitial cystitis/bladder painful syndrome (IC/BPS) has been demonstrated, but the role of IL‐6 in IC/BPS and its source remain to be explored." (PMID 34407316, 2021). "However, IL-6 in urine seems to be nonspecific and a characteristic for chronic inflammation, as its upregulation is observed in patients with interstitial cystitis." (PMID 33381567, 2020).